HIF1A (hypoxia inducible factor 1 subunit alpha)
Diseases named in the same sentence as HIF1A in open-access papers (continued):
Sharing a sentence is not in itself a finding about the gene and the disease.
colorectal cancer (continued). "In an in vitro study we recently reported that HIF-1α upregulation in response to hypoxia was accompanied by a significantly increased production of vascular endothelial growth factor (VEGF) in two of five colorectal carcinoma cell lines." (PMID 18983642, 2008). "However, the role of HIF-1α in tumor progression of colorectal carcinomas is still unclear and the published data so far are controversial." (PMID 18983642, 2008). "Similarly, in breast and colorectal cancers, B7-H3 exerts comparable effects by inhibiting Nrf2, thereby regulating critical metabolic enzymes such as hypoxia-inducible factor 1-alpha (HIF1α), lactate dehydrogenase A (LDHA), and pyruvate dehydrogenase kinase 1 (PDK1)." (PMID 40214484, 2025). "Additionally, in colorectal cancer cells, the activated PI3K/AKT pathway was recently reported to upregulate HIF‐1α expression in 5‐FU‐resistant colorectal cancer cells, thereby increasing the expression of membrane transport proteins to increase glucose flux and enhance glycolysis." (PMID 40452814, 2025). "Consistent with this hypothesis, our group recently observed that CTCs isolated from colorectal cancer patients who rapidly progressed in course of treatment with chemotherapy plus antiangiogenic drugs co-express HIF-1α and vimentin in response to prolonged drug exposure (unpublished data)." (PMID 37540301, 2023). "HIF-1α could bind directly to the proximal promoter of ZEB1 via HRE in colorectal cancer cells." (PMID 32322559, 2020). "Taken together, these results verified that AAM effectively inhibits migration and VM formation by suppressing ROS/HIF-1α/MMP2 pathway in colorectal cancer under hypoxic condition, suggesting AAM could serve as a therapeutic agent to inhibit VM formation in human colorectal cancer." (PMID 32499699, 2020). "Therefore, XIST may work as a miR‐93‐5p ceRNA and modulate the level of HIF‐1A in the development process of colorectal cancer." (PMID 32061057, 2020). "Interestingly, we have previously found that miR-638 may be involved in the regulation of glucose metabolism in colorectal cancer by targeting HIF-1α and PGK1." (PMID 29069781, 2017). "In phase II, we focused on five HIF-coding genes (HIF1A, HIF1B, HIF2A, HIF2B and HIF3A) and two hypoxia-inducible genes (LOX and CXCL12) and investigated the relationship of their SNPs (n = 77) with the risk of outcome in an additional colorectal cancer patient cohort (n = 535)." (PMID 25405996, 2014). "Indeed, leptin and OBR expression is correlated with HIF-1α in endometrial and colorectal cancer, which suggests that HIF-1α may induce both." (PMID 23425972, 2013). "The robust gene HIF1A might be ignored in the colorectal cancer expression analysis." (PMID 24350280, 2013). "HIF1α-mediated RHOA upregulation has been suggested across multiple types of cancers, including hepatocellular, lung, breast and colorectal cancer." (PMID 40600795, 2025). "These discoveries offer new pharmacological strategies to inhibit HIF1α expression, like MPG peptides, potentially serving as an effective treatment for colorectal cancer, particularly in patients resistant to anti‐angiogenic therapies." (PMID 39964832, 2025). "In colorectal cancer, PRMT3 promotes tumorigenesis through dual mechanisms whereby it stabilizes HIF1α and METTL14 in a methylation-dependent manner, thereby enhancing glycolysis, angiogenesis, and inflammation." (PMID 41583428, 2025). "In colorectal cancer (CRC), SENP1 contributes to drug resistance by stabilizing HIF-1α, thereby enhancing survival, migration, and metabolic adaptation under stress conditions." (PMID 39859203, 2025).
colorectal cancer (continued). "In colorectal cancer, which is characterized by elevated METTL3 and HIF-1α levels, METTL3 knockdown reduced the m6A modification of HIF1A and lowered its translation efficiency, leading to the suppression of the Warburg effect." (PMID 40102715, 2025). "For instance, 5'tiRNA‐His‐GTG, a tsRNA regulated by the hypoxia‐inducible factor 1 subunit alpha (HIF1α)/ANG axis, was identified to play an oncogenic role in the progression of colorectal cancer, by suppressing hippo signalling." (PMID 39993386, 2025). "Recently, multiple circRNAs have been found to be overexpressed in colorectal cancer (CRC) and to facilitate proliferation, migration, and metastasis through the upregulation of HIF-1α." (PMID 40305214, 2025). "In colorectal cancer, PRMT3 binds to HIF-1α and methylates its Arg803 residue, inhibiting HIF-1α’s ubiquitin-mediated degradation and activating glycolytic genes." (PMID 41583428, 2025). "In a colorectal cancer model, OMA1 promoted a shift towards glycolysis via HIF‐1α stabilization, effectively suppressing OXPHOS in favor of glycolytic ATP production." (PMID 41388823, 2025). "HIF-1α: hypoxia inducible factor-1 alpha, CRC: Colorectal cancer, n: number, SD, standard deviation, T: tumor size, N: nodes." (PMID 38313904, 2024). "In our previous study, we determined vitamin C was able to induce HIF1a hydroxylation and degradation, downregulating GLUT1 and PDK1 in KRAS mutant colorectal cancer." (PMID 38425123, 2024). "HIF-1α: hypoxia inducible factor-1 alpha, CRC: Colorectal cancer, IL-33: Interleukin-33, IQR: interquartile range, n: number, T: tumor size, N: nodes." (PMID 38313904, 2024). "HIF-1α: hypoxia inducible factor-1 alpha, CRC: Colorectal cancer, VEGF: vascular endothelial growth factor, IQR: interquartile range, n: number, T: tumor size, N: nodes." (PMID 38313904, 2024). "Deacetyltransferase HDAC1 is able to inhibit HIF1α ubiquitination degradation process, which in turn activates HIF1α/VEGF-A signaling pathway to promote angiogenesis in colorectal cancer." (PMID 38687357, 2024). "LRG1 has been shown to increase angiogenesis in ocular diseases and in colorectal cancer, by promoting the expression of vascular endothelial growth factor (VEGF) in a Hypoxia-inducible factor-1 alpha (HIF-1α)-dependent fashion." (PMID 37513518, 2023). "Previous studies have also shown that saffron treats diseases through the HIF-1α/VEGF signaling pathway, and crocin inhibits angiogenesis and metastasis of colorectal cancer cells by targeting NF-κB and blocking the TNF-α/NF-κB/VEGF pathway." (PMID 37959658, 2023). "HIF-1a is ubiquitinated and degraded by NEDD4L to inhibit colorectal cancer angiogenesis and enhance sensitivity to bevacizumab." (PMID 38027016, 2023). "This implied that tan IIA potentially impeded colorectal cancer’s spread by blocking the β-catenin/TCF3/LEF1 signaling pathway via the suppression of TGF-β1, HIF-1α." (PMID 37964867, 2023). "However, its impact on HIF-1α in colorectal cancer (CRC) cell migration is unknown." (PMID 37583906, 2023). "On the other hand, there is evidence that HIF1A mRNA is overexpressed in CC and laryngeal squamous cell carcinoma, while GLUT1 is overexpressed in CC and colorectal cancer." (PMID 36678382, 2022). "The inhibition of STAT3 as well as hypoxia inducible factors (HIF-1α) and MAPK/NF-kB signalling pathways are also involved in the suppression of colorectal cancer." (PMID 35897965, 2022). "CSN8 increases HIF-1α mRNA expression, stabilizes the HIF-1α protein by reducing its ubiquitination, induces the epidermal-mesenchymal transition (EMT) of primary colorectal cancer cells, and increases migration and invasion." (PMID 35392171, 2022).
colorectal cancer (continued). "In colorectal cancer, XIST also augments the level of HIF-1α via negatively regulating miR-93-5p activity; therefore, XIST can possess stimulatory effects on migration, invasion, and the EMT process." (PMID 34298879, 2021). "In colorectal cancer cells, KDM4B expression is induced by HIF-1α, and KDM4B upregulates the expression of hypoxia-inducing genes such as carbonic anhydrase 9 (CA9) by decreasing H3K9me3 markers in the promoter." (PMID 35186950, 2021). "To confirm the interaction between Smurf2 and HIF-1α, we performed a co-immunoprecipitation assay in the HCT116 colorectal cancer cell line." (PMID 34611473, 2021). "Studies have reported that hypoxia can promote disease development and metastasis by activating the HIF1α/VEGFA pathway in breast and colorectal cancer." (PMID 34610581, 2021). "Overexpression of prolidase in colorectal cancer cells contributed to increase in nuclear hypoxia-inducible factor (HIF-1α) level and HIF-1α-dependent gene products, e.g., vascular endothelial growth factor (VEGF) and glucose transporter-1 (Glut-1)." (PMID 33818628, 2021). "The universal effect of HIF1α inhibition by combination of CDK1 knockdown and HSP90 inhibition among various colorectal cancer cell lines prompted us to investigate the therapeutic potential of such combination strategy." (PMID 34686682, 2021). "In colorectal cancer, the hypoxia-induced lncRNAs XIST and LINC00511 down-regulate respectively the miR-93-5p and the miR-153-5p, which both have HIF-1α mRNA among their targets." (PMID 33673376, 2021). "Based on the 2020 TCGA data, the overexpression of HIF1α target genes VEGFA and SLC2A1 correlated with poor disease-free prognosis in colorectal cancer." (PMID 34686682, 2021). "The expression of both HIF-1α and ABCB1 is reduced by ursolic acid in hypoxic colorectal cancer cells." (PMID 34575983, 2021). "In the early stage, our group established a correlation between GLUT-1 and HIF-1α by establishing molecular imaging features of liver metastasis nodules (18F-FMISO and 18F-FDG), in order to achieve early diagnosis of colorectal cancer liver metastasis." (PMID 33712897, 2021). "We also tested another colorectal cancer cell line, SW480, in which overexpression of Smurf2 similarly reduced HIF-1α expression level under hypoxia." (PMID 34611473, 2021). "In colorectal cancer, lncRNA HITT, in cooperation with Ezh2, inhibits HIF-1α transcription and inhibits hypoxia adaptation in colorectal cancer cells." (PMID 34888249, 2021). "Some studies have found that Akt1 signaling significantly suppresses the expression of MMP2, MMP9, HIF1α, and VEGF in colorectal carcinoma cells." (PMID 34394377, 2021). "TIP60 acts as a transcriptional coactivator of HIF-1α, affecting chromatin structure and regulating HIF target genes in colorectal cancer." (PMID 33109235, 2020). "XIST is the competitive endogenous RNA of miR‐93‐5p to promote HIF‐1A, and then the upregulated AXL level facilitates the EMT process, migration, and proliferation of colorectal cancer." (PMID 32061057, 2020). "In colorectal cancer, garcinol has been reported to act through microsomal prostaglandin E synthase-1 (mPGES-1)/prostaglandin E synthase 2 (PGE2)/hypoxia inducible factor-1 alpha (HIF-1α) axis in HT-29 cells." (PMID 32365899, 2020). "Ptbp3 can promote the growth and metastasis of colorectal cancer through the activation of HIF-1α, and HIF-1α is involved in the ICH process." (PMID 32602850, 2020). "IL-6 is also known to act via hypoxia-inducible factor (HIF)-1α to increase VEGF expression and this process has been shown to be inhibited by miR-451 mediated regulation of IL-6R expression in colorectal cancer cells." (PMID 32321512, 2020). "LOX activated by HIF-1α can further induce HIF-1α through PI3K/AKT signaling, a process that involves LOX-generated H2O2 promoting colorectal carcinoma cell proliferation and in vivo tumor growth." (PMID 32708046, 2020).
colorectal cancer (continued). "HIF1α/hypoxia inducible factor 1 alpha Oxygen deprivation of damaged tissues induces the expression of HIF1α that regulates SNAI1, ZEB1, and β-catenin, thereby activating EMT and contributing to fibrosis formation and colorectal cancer development." (PMID 31752264, 2019). "HIF-1α is an essential mediator of cellular response to hypoxia and VEGF is a potent angiogenic factor, both are overexpressed in colorectal cancer and prognostic indicators of poor outcome." (PMID 31624493, 2019). "HIF-1α also binds to β-catenin by competing with transcription factor 4 (TCF4), thereby inducing EMT in colorectal cancer." (PMID 30671168, 2018). "al. observed HIF1-α levels in brain metastasis samples from RCC, melanoma, breast, lung and colorectal cancer by immunohistochemistry." (PMID 29202733, 2017). "We demonstrated that miR-1 suppressed aerobic glycolysis while Smad3 promoted it via its downstream effecter HIF-1α and glycolytic enzymes, including HK2, MCT4, in colorectal cancer." (PMID 28471448, 2017). "We performed IHC and scored the results in TMA consisting of 79 patients with stage I-III colorectal cancer and corresponding adjacent normal tissues (ANT) to test the expression status of RPS7, HIF-1α, GLUT4 and LDHB." (PMID 26735579, 2016). "Immunohistochemical analysis of colorectal cancer tissues demonstrates that high NQO1-expressing tumours, indicating 3 and 4 of IHC scores, contain a significantly elevated expression of HIF-1α." (PMID 27966538, 2016). "Overexpression of HIF-1α and CA9 have also been shown to be powerful prognostic factors in colorectal cancers." (PMID 25789026, 2015). "Recently the central role of HSP90 in regulation of both HIF-1a and STAT-3 and a strong antiangiogenic effect of ganetespib were confirmed in colorectal cancer." (PMID 26517240, 2015). "In contrast, another study showed that HIF-1α, in cooperation with heat shock protein 90, regulates STAT3 activation and expression in colorectal cancer cells." (PMID 26272737, 2015). "HIF1α-independent PAFC16 accumulation in hypoxia was confirmed in hif1αKD DLD-1 and SW1222 colorectal cancer cells." (PMID 25605240, 2015). "Due to the crucial role of HIF-1α and CXCR4/CXCL12 in the metastatic process of colorectal cancer, we determined CXCR4 and CXCR7 gene expression in human colon carcinomas and their modulation by hypoxia and HIF-1α in colon cancer cell lines." (PMID 24629239, 2014). "Our aim was to study the significance of targeting HIF-1α and the CXCR4/CXCL12 axis in colorectal cancer to prevent the dissemination process in vitro." (PMID 24629239, 2014). "In the first phase, 49 SNPs from six hypoxia pathway genes (HIF1A, HIF1B, HIF2A, LOX, MIF and CXCL12) in 272 colorectal cancer patients were analyzed." (PMID 25405996, 2014). "Taken together, these results indicate the potential of targeting HIF-1α and CXCR4/CXCL12 in colorectal cancer." (PMID 24629239, 2014). "Hypoxia induces stabilisation of HIF1α and its interaction with β-catenin, thereby competing with TCF/LEF1 transcription factors for β-catenin binding in colorectal cancer cells." (PMID 18506144, 2008). "For example, methylation of HIF1α by PRMT3 could enhance angiogenesis and glycolysis, influencing colorectal cancer development; in glioblastoma, it might promote cell proliferation; and in breast cancer, assist in inducing apoptosis." (PMID 39964832, 2025). "While HIF-1α and HIF-2α expressions are generally associated with poor prognosis in colorectal cancers, some studies have failed to establish their independent prognostic value." (PMID 39857068, 2025). "Additionally, hypoxic repression of miR-338-5p stabilizes a HIF-1α-driven feedback loop via direct targeting of IL-6/STAT3/Bcl2 signaling, driving chemoresistance in colorectal cancer." (PMID 40305214, 2025).
colorectal cancer (continued). "Mechanically, the response process of 5’ tiRNA-His-GTG to the tumor hypoxic microenvironment, regulated by the HIF1α/ANG axis, reveals a specific pathway of 5’ tiRNA-His-GTG involved in colorectal cancer progression and provides clues for the design of new colorectal cancer therapeutic targets." (PMID 40726981, 2025). "This mutual amplification mirrors feedback loops observed in other cancers, such as the NAT10/SEPT9/HIF-1α axis in gastric cancer glycolysis and the NAT10/KIF23/GSK-3β axis in colorectal cancer progression, underscoring the critical role of NAT10 in sustaining oncogenic signaling networks." (PMID 40999468, 2025). "In colorectal cancer cells, for example, BPA induces the overexpression of GOLPH3, which promotes malignant behavior by activating the PI3K/AKT/mTOR cascade and ROS-driven HIF-1α/VEGF signaling, even under hypoxic conditions." (PMID 41440754, 2025). "Additionally, thymol exhibits anti‐EGFR activity, while carvacrol modulates the HIF‐1α/VEGF pathway, making them potential candidates for colorectal cancer (CRC) management." (PMID 40964147, 2025). "Worenine, an alkaloid from Coptis chinensis Franch., targets HIF1α to decrease glycolytic activity and downregulate the expression of glycolytic enzymes (PFK-L, HK2, and PKM2), thereby inhibiting colorectal cancer cell growth, proliferation, and cell cycle progression." (PMID 39330497, 2024). "The PI3K/AKT pathway plays a pivotal role in the onset and progression of colorectal cancer, influencing autophagy, apoptosis, and EMT-mediated cancer cell migration and invasion, accompanied by regulation of CCND1, mTOR, FOXO, HIF-1α, CASP, Bax, and Bcl-2 expression." (PMID 38384287, 2024). "As a competitive sponge for miR-93-5p, XIST may act as a positive regulator of HIF-1A, which in turn increased expression of AXL, and thus promoted the EMT process, as well as migration and proliferation in colorectal cancer." (PMID 39830506, 2024). "Specifically, HIF-1α enhances glycolysis and PPP by regulating the expression of pyruvate kinase M2 (PKM2) and glucose-6-phosphate dehydrogenase (G6PD) to impart 5-fluorouracil resistance in colorectal cancer." (PMID 39343971, 2024). "In colorectal cancer (CRC) and ulcerative colitis (UC), the afa-1 operon in E. coli has been demonstrated to induce the overexpression of HIF-1α and upregulate the expression of IL-8, VEGF, and Twist1 genes, while simultaneously downregulating the expression of E-cadherin." (PMID 39710789, 2024). "As an inhibitor of HIF-1α, IDF-11774 could decrease HIF-1α and exert anticancer effects in colorectal cancer and melanoma." (PMID 38140111, 2023). "IDF-11774 hinders HIF-1α accumulation through multiple mechanisms, including the stimulation of proteasomal degradation under hypoxic conditions, inhibition of HSP70 activity, and modulation of cancer glycolytic metabolism in colorectal cancer." (PMID 38140111, 2023). "Of note, our preliminary and encouraging results indicate that the SLAB51 lysate was able to counteract the stabilization of HIF-1α in different human colorectal cancer cell lines, i.e., HT29 and HCT116 (not shown)." (PMID 37175841, 2023). "Other proteins, including TIMP-2, IGF-1, and HIF-1α, demonstrate increased expression in clones of peritoneal metastasis from colorectal cancer as opposed to primary colorectal tumors or liver metastases originating from colorectal cancer." (PMID 37689664, 2023). "For instance, HIF1A displaces MYC binding from the promoter of cyclin-dependent kinase inhibitor 1A (CDKN1A, p21cip1) and upregulates the expression of p21 (CDKN1A) in human HCT116 colorectal carcinoma cell line." (PMID 37998757, 2023). "Niclosamide inhibits HIF1α signaling to enhance the effects of radiation in non-small cell lung cancer and blocks EGF-induced HIF1α signaling to repress tumorigenesis and invasion in colorectal cancer." (PMID 36479072, 2022).